OR4D10 (olfactory receptor family 4 subfamily D member 10)
Description:
Odorant receptor.
Synonyms: OR4D10P; OST711; OR11-251
Tractability: Antibody: UniProt places it where antibodies can reach, with medium confidence; UniProt predicts a signal peptide or a membrane-spanning region; its Gene Ontology location is reachable by antibodies, with medium confidence.
Gene: Protein-coding gene on chromosome 11 (59,473,315 to 59,479,361, forward strand). Ensembl gene ENSG00000254466.
Subcellular location: Cell membrane
Pathways (Reactome):
Sensory Perception: Expression and translocation of olfactory receptors
Gene Ontology:
Molecular function: olfactory receptor activity; G protein-coupled receptor activity
Biological process: detection of chemical stimulus involved in sensory perception of smell; G protein-coupled receptor signaling pathway
Cellular component: plasma membrane; membrane
Genetic constraint (gnomAD): Loss-of-function variants: 1 observed, 2.93 expected, observed/expected ratio (o/e) 0.34, 90% interval 0.12 to 1.49. That is too few expected variants to judge how well the gene tolerates losing a copy. Missense variants: 390 observed, 385.73 expected, observed/expected ratio (o/e) 1.01, 90% interval 0.93 to 1.1. Synonymous variants: 186 observed, 156.93 expected, observed/expected ratio (o/e) 1.19, 90% interval 1.05 to 1.34.
Homologues: Orthologues: chimpanzee OR4D10 (98% identical), macaque OR4D10 (91% identical), dog OR4D10 (89% identical), rabbit OR4D10 (86% identical), mouse Or4d10 (86% identical), rat Or4d10 (86% identical), mouse Or4d10c (85% identical), rat Or4d10c (85% identical), mouse Or4d10b (84% identical), pig OR4D10 (81% identical). Paralogues in human: OR4D11 (81% identical), OR4D9 (79% identical), OR4D6 (65% identical), OR4D1 (61% identical), OR4D2 (60% identical), OR4D5 (57% identical), OR4E2 (49% identical), OR4N5 (49% identical), OR4A15 (49% identical), OR4A47 (48% identical), OR4C6 (48% identical), OR4E1 (48% identical), and 116 more.
Diseases named in the same sentence as OR4D10 in open-access papers:
OR4D10 is named in the same sentence as 4 diseases in open-access papers, as found by Europe PMC text mining. Sharing a sentence is not in itself a finding about the gene and the disease. The quoted sentences say what the papers report.
thyroid cancer (1 paper, 2025). "The findings imply that elevated expression of GZMK, TREM2, and OR4D10 is linked to the hyperactivation of several oncogenic pathways in thyroid cancer, including those that regulate cell division." (PMID 40332815, 2025). "To further understand the functions and pathways influenced by GZMK, TREM2, OR4D10, and all other mRNAs in thyroid cancer, we performed correlation studies using TCGA data." (PMID 40332815, 2025). "GZMK, TREM2, and OR4D10 were strongly expressed in several kinds of malignancies including thyroid cancer." (PMID 40332815, 2025). "Specifically, in THCA, we observed lower GZMK and higher TREM2 and OR4D10 expression in tumor tissues compared to adjacent normal tissues, suggesting their involvement in thyroid cancer pathogenesis." (PMID 40332815, 2025). "In conclusion, our study provides new insights into the expression patterns and potential roles of GZMK, TREM2, and OR4D10 in pan-cancer, with a particular focus on thyroid cancer." (PMID 40332815, 2025). "The current study presents a comprehensive analysis of the expression patterns and potential roles of GZMK, TREM2, and OR4D10 in pan-cancer, with a particular focus on thyroid cancer (THCA)." (PMID 40332815, 2025). "In this study, we aimed to comprehensively investigate the expression patterns, prognostic significance, and functional roles of GZMK, TREM2, and OR4D10 in thyroid cancer." (PMID 40332815, 2025). "Our findings suggest that GZMK, TREM2, and OR4D10 may play important roles in modulating the immune response in thyroid cancer, potentially through their effects on leukocyte cell–cell adhesion and mononuclear cell differentiation." (PMID 40332815, 2025). "According to our research, OR4D10, TREM2, and GZMK could all be genes associated with thyroid cancer." (PMID 40332815, 2025). "This suggests that the development of thyroid cancer is linked to GZMK, TREM2, and OR4D10." (PMID 40332815, 2025). "TREM2 was linked to M staging and pathological staging, OR4D10 was linked to T, N, and pathological staging, and GZMK was linked to T, N, M, and pathological staging, according to our analysis of the expression of these three proteins in the development of thyroid cancer." (PMID 40332815, 2025). "This suggests that GZMK, TREM2, and OR4D10 may be involved in the pathogenesis of thyroid cancer." (PMID 40332815, 2025). "In particular, THCA thyroid cancer in the TCGA cohort had lower GZMK, higher TREM2, and higher OR4D10 expression compared to the adjacent tissues." (PMID 40332815, 2025).
cancer (1 paper, 2025). A tumor composed of atypical neoplastic, often pleomorphic cells that invade other tissues. "OR4D10, an olfactory receptor, although less studied in cancer, has been suggested to have functions beyond olfaction, including potential roles in cell proliferation and migration." (PMID 40332815, 2025). "First, we looked at the expression of GZMK, TREM2, and OR4D10 in the pan-cancer datasets GTEx and TCGA." (PMID 40332815, 2025). "Among these, GZMK, TREM2, and OR4D10 have emerged as promising candidates due to their involvement in immune regulation and cellular processes that are often dysregulated in cancer." (PMID 40332815, 2025). "Furthermore, our analysis of the association between GZMK, TREM2, and OR4D10 expression and cancer patient prognosis in the TCGA cohort demonstrated that reduced expression of GZMK and increased expression of TREM2 and OR4D10 were significantly correlated with poor prognosis in THCA." (PMID 40332815, 2025). "Additionally, it would be interesting to investigate the potential interactions between GZMK, TREM2, and OR4D10 and other immune-related genes in the tumor microenvironment, which could provide new insights into the complex interplay between cancer cells and the immune system." (PMID 40332815, 2025). "Genotype–tissue expression pan-cancer data and The Cancer Genome Atlas (TCGA) were used to investigate the expression of GZMK, TREM2, and OR4D10." (PMID 40332815, 2025). "To assess the usefulness of GZMK, TREM2, and OR4D10 expression in predicting the prognosis of cancer patients, we examined the relationship between GZMK, TREM2, and OR4D10 expression and overall survival in the TCGA cohort." (PMID 40332815, 2025). "The results demonstrated that a poor prognosis in THCA was substantially correlated with reduced expression of GZMK, TREM2, and OR4D10 (p = 0.041, 0.024, and 0.017), suggesting that GZMK, TREM2, and OR4D10 are the potential oncogenes in this cancer." (PMID 40332815, 2025).
tumor (1 paper, 2025). "This image displays a box and dot plot of the GZMK, TREM2, and OR4D10 gene expression distributions in tumor and normal tissues." (PMID 40332815, 2025).
OR4D10 also shares sentences with these, for which no sentence is quoted: Obesity (1 paper).